CD86 (CD86 molecule)
Diseases named in the same sentence as CD86 in open-access papers (continued):
Sharing a sentence is not in itself a finding about the gene and the disease.
Sepsis (continued). "Together suggesting CD28, through either CD80 or CD86 is capable of mediating the inflammatory response and lethality of polymicrobial sepsis." (PMID 19672303, 2009). "Specifically, sepsis was associated with an increase in CD80 expression, while there appeared to be a downregulation of constitutive CD86 expression." (PMID 19672303, 2009). "We next sought to determine the relative contributions of CD80 and CD86 to mortality and inflammatory cytokine production in polymicrobial sepsis." (PMID 19672303, 2009). "Another potential reason for the prominent effect for CD80 in innate immunity, centers on the differential expression of CD80 and CD86 in sepsis." (PMID 19672303, 2009). "While our data provide strong evidence for a predominant role for CD80 in regulation of lethal inflammation in sepsis, the role for CD86 remains conflicted." (PMID 19672303, 2009). "Notably, HLA-DRA, IL1B, and CD86 were prominently elevated in Microglia 2 from sepsis patients, while P2RY12 and TREM2 were reduced, further supporting a pro-inflammatory shift." (PMID 41030458, 2025). "Analysis of H&E-stained lung sections in the LPS-induced sepsis model revealed heightened histopathological changes such as alveolar septa thickening, congestion of alveolar spaces, and CD86 expression, which was significantly alleviated by PLP co-administration." (PMID 40384854, 2025). "Reduced monocyte HLA-DR and CD86 suggest that the monocyte phenotype in sepsis may be driving an anti-inflammatory phenotype in T-lymphocytes; supporting the utility of monocyte HLA-DR as a biomarker to identify patients with sepsis immunoparalysis." (PMID 41573541, 2025). "CD86 is an independent predictor of the occurrence of sepsis in patients with infection in the emergency department and has a certain value in the early clinical diagnosis of sepsis in such patients." (PMID 38603712, 2024). "Furthermore, in vivo experiments revealed that depletion of FGF2 in macrophages worsened sepsis-induced lung inflammation, lung vascular leak, and lung histological injury, accompanied by an increase in CD86-positive cells and apoptosis." (PMID 39436561, 2024). "Therefore, this study aimed to explore the value of the costimulatory molecule CD86 in the early diagnosis of sepsis in the emergency department and the value of HLA in the prognosis of patients with sepsis." (PMID 38603712, 2024). "Therefore, the early elevation of CD86 in patients with sepsis is consistent with the known immune mechanisms." (PMID 38603712, 2024). "Interestingly, under continuing stimulation of LPS, a similar situation as sepsis condition, EgCF still has the ability to reduce M1 (F4/80+CD11b+CD86+) and boost M2 (F4/80+CD11b+CD206+) macrophages." (PMID 38066526, 2023). "However, molecular mechanisms responsible for the establishment of immune-suppressive monocytes with reduced expression of immune-enhancing mediators such as CD86 during sepsis are not well understood." (PMID 38162637, 2023). "Exosomes derived from adipose stem cells could reduce the expression of IL-1β, TNF-α and IL-6 in macrophages during sepsis while also downregulating M1 markers (iNOS and CD86) expression." (PMID 37635258, 2023). "Thus, the downregulation of HLA-DR and CD86 are suggestive of a state of immune suppression in sepsis." (PMID 34566996, 2021). "According to the dynamics of HLA‐DR and CD86 in sepsis, we determined the frequency of HLA‐DRlow,neg CD86low,neg cells in all monocyte subsets and revealed a significantly increased frequency of HLA‐DRlow,neg CD86low,neg in early deceased patients in comparison to patients, who survived day five." (PMID 32949213, 2020). "In addition, breast cancer and sepsis HLA-DRlow/- monocytes, when compared to HLA-DR++ monocytes, displayed significantly reduced levels of the co-receptors CD86, CD80 and the suggested anti-inflammatory monocyte-macrophage marker CD163." (PMID 25992611, 2015).
Sepsis (continued). "Consequently, the goals of this study were to determine the individual contribution of CD28, CD80 and CD86 to the inflammatory response in murine sepsis, and to better correlate expression of these molecules with outcome in humans with sepsis and septic shock." (PMID 19672303, 2009). "Notably, Study have shown that IL-37 could significantly downregulate the expression of HLA-DR and CD86 in septic mice, inhibiting antigen presentation and indicating an immunosuppressive effect in sepsis." (PMID 40364841, 2025). "Furthermore, we validated the reduction in CD86 levels in monocytes collected from wild-type mice but not TRAM-deficient mice following the onset of mild sepsis, highlighting TRAM’s involvement in monocyte exhaustion in vivo." (PMID 38162637, 2023). "Additionally, CD80 and CD86 cell surface markers expressed by activated monocytes/macrophages have a differential role in the regulation of inflammation, especially in the innate immune response to sepsis." (PMID 37761018, 2023). "Finally, we sought to expand our previously reported data and determine whether differential expression of CD80 and CD86 occurred in humans with sepsis and if expression levels could serve as biomarkers for outcome." (PMID 19672303, 2009). "Myeloid dendritic cells (mDCs) were less abundant in sepsis patients, while upregulation of CD25 and CD86 on their surface suggest an immunoregulatory capacity." (PMID 40486505, 2025). "Compared to the control group, signaling pathways such as ANNEXIN, CCL, and CADM showed enhanced relative information flow in sepsis samples, whereas classical immune-related pathways such as MHC-II, APP, IL16, and CD86 were markedly suppressed." (PMID 41346577, 2025). "Especially in sepsis patients, monocytes presented the lowest CD39, CD86 and HLA–DR expressions than mild infection and surgery patients." (PMID 40065471, 2025). "sPLA2 can enhance the expression of CD86, CD80, CD83, and CD40 on the surface of DCs, promote DC maturation, and improve the prognosis of sepsis (ClinicalTrials.gov ID NCT00034476)." (PMID 38816685, 2024). "The AUC of the model composed of CD86%, PLT, IL-10, and PCT to predict the occurrence of sepsis was 0.870 (0.800 sensitivity and 0.857 specificity)." (PMID 38603712, 2024). "The suppressed expression of CD80, CD86, and MHC-II was reversed by inhibiting cerebral HMGB1 at 48 h after sepsis." (PMID 34512319, 2021). "AuNP also decreased M1 macrophages (CD86 + ve in F4/80 + ve cells) and increased M2 macrophages (CD206 + ve in F4/80 + ve cells) in the spleens of sepsis mice." (PMID 30119646, 2018). "Another evidence of the differential function of CD80/CD86 was a study demonstrating that CD80−/− mice had improved survival in a cecal ligation and puncture sepsis model when compared to wild-type or CD86−/− mice." (PMID 24367573, 2013). "The CD86%, neutrophil count, CRP/ALB, NLR, IL-6, IL-10, sIL-2R, CRP, and PCT levels were significantly higher, and the HLA-DR%, lymphocytes, PLT, and ALB levels were significantly lower in the sepsis group than in the non-sepsis group (all P<0.05)." (PMID 38603712, 2024). "CD86 levels were significantly reduced in wild type, but not TRAM deficient mice following the onset of mild sepsis." (PMID 38162637, 2023). "The ratio of DCs expressing MHC-II, CD86, and CD80, the mRNAs level of dendritic cells expressing TNF-α and IL-12, and the level of DC-mediated T-cell proliferation were all decreased, both in vivo and in vitro during sepsis, when PINK1 was knocked out." (PMID 36809929, 2023). "It was found that the percentages of MHCII, CD40, CD80, and CD86 on surface of DCs obviously increased in the sepsis-induced ALI group when compared to the control and GTS-21-positive control mice group, and the increase in MHCII, CD40, and CD86 was reduced through GTS-21 intervention." (PMID 35125962, 2022). "The expressions of CD80, CD86, and MHC-II were all increased at 24 h after the induction of sepsis." (PMID 34512319, 2021).
Sepsis (continued). "Compared to healthy donors (n = 18), the sepsis patients exhibited a significantly fewer percentage and number of pDCs and cDCs, and a lower expression of antigen presenting molecule HLD-DR and co-stimulatory molecules (e.g., CD86) on the surface of DCs." (PMID 34566996, 2021). "The expression of HLA-DR on the surface of pDCs derived from the children with sepsis in the early stage of disease was significantly lower compared with that of the health donor group, whereas the level of CD86 did not change significantly." (PMID 34566996, 2021). "On the other hand, the expressions of CD80 on both SP DCs and MLN DCs, and those of CD86 on SP DCs, were shown to be increased by sepsis; however, neither marker was significantly higher on MLN DCs compared to SP DCs in septic mice." (PMID 31323786, 2019). "The differential changes in CD80 and CD86 expression on CD11c+ DCs during the early and late phases of our sepsis model suggest that CD80+ and CD86+ are differentially modulated due to sepsis, so we determined whether SIRT1 inhibition balances this pattern." (PMID 30069485, 2018). "Although CD86 was expressed on virtually all CD14+ monocytes, the expression was substantially decreased in a subpopulation of patients with LRR/MBC as well as in patients with sepsis." (PMID 25992611, 2015). "The potential value of CD86 for sepsis prediction has not been explored so far." (PMID 38603712, 2024). "Functional markers such as CD40, CD80, CD86, and MHC-II were significantly upregulated by DCs in animal sepsis models during the initial phase of sepsis, which is essential for the activation of T cells, while DCs downregulated the expression of surface molecules at the late stage of sepsis." (PMID 38816685, 2024). "In addition, the CD86% in PBMCs was higher in the sepsis group than in the non-sepsis group, which contradicts the results of some previous studies, but this finding is more in line with the pathophysiological characteristics of sepsis." (PMID 38603712, 2024). "The CD86 mRNA levels of patients who died of sepsis were decreased, but the lack of statistically significant differences among the groups might be related to polymorphisms in the CD86 gene or different post-transcriptional or post-translational regulation." (PMID 38603712, 2024). "However, AuNP treatment intriguingly showed the reduced percentage of pro-inflammatory macrophage (M1; F4/80+ and CD86+) and the increased percentage of anti-inflammatory macrophage (M2; F4/80+ and CD206+) in sepsis as demonstrated by the flow-cytometric analysis." (PMID 30119646, 2018). "The ability of CD28 to regulate inflammation in the innate immune response to sepsis is consistent with prior reports documenting CD28 expression on PMNs and the ability of CD28, either soluble or in PMN lipid rafts, to induce NF-κB and pro-inflammatory cytokine production via CD80/CD86." (PMID 19672303, 2009). "In addition, the expression of RELMα and CD86 on peritoneal macrophages was not altered by TGFβ depletion, indicating that the L. sigmodontis-induced macrophage modulation is not due to TGFβ during acute sepsis." (PMID 31815088, 2019). "Expressions of CD40, CD86, PD-1, PD-L1, TIM-3 and LAG-3 were not changed on B220+ lymphocytes after sepsis." (PMID 40155394, 2025). "Finally, the improved survival with anti-CD80 as opposed to anti-CD86 confirms the results obtained with the knockout mice and the ability of anti-CD80 to rescue mice when given after the onset of sepsis suggests this is a potential therapeutic target as well." (PMID 19672303, 2009). "Moreover, the treatment with DIDS did not reverse the number of Iba-1-, CD86- and iNOS-positive cells, nor affected microglia branching, although previous studies demonstrated that DIDS can inhibit the expression and secretion of serum IL1-α and macrophage activation in a sepsis animal model." (PMID 31575916, 2019).
glioma (51 papers, 2011 to 2025). A benign or malignant brain and spinal cord tumor that arises from glial cells (astrocytes, oligodendrocytes, ependymal cells). "Furthermore, we observed that GAMs in IDHmt gliomas exhibited a significant increase in the expression of M1‐associated markers and cytokines, such as CD86 and IL1B, and a significant decrease in M2‐associated genes, such as CD163 and CD206, relative to IDHwt counterparts." (PMID 37166058, 2023). "This study aimed to evaluate the potential of cluster of differentiation 86 (CD86) as a biomarker in high-grade glioma (HGG)." (PMID 38154107, 2023). "The expression of PANK1 in the high immune cell infiltration group was significantly lower than that in the low immune cell infiltration group using the M1 macrophage marker, CD86, in glioma tissues (Spearman r= -0.65, P<0.01)." (PMID 37138430, 2023). "We next evaluated the presence of DCs in gliomas by performing immunofluorescence staining for CD86, a maturation marker overexpressed on activated tumor-infiltrating DCs." (PMID 35386310, 2022). "In this study, we comprehensively analyzed the prognostic value of CD86 expression in pan-cancer, and found that CD86 acts as an unfavorable factor in the progression and prognosis of lower-grade glioma (LGG)." (PMID 33954112, 2021). "The univariate Cox regression showed that the expression levels of PD-L2, TIM3, CD80, CD86, CD155, and CIITA were risk factors for glioma in all glioma population and the HGG population." (PMID 33996602, 2021). "JWH133 treatment also significantly increased the mRNA level of M2 subtype markers CD206, Arg1, and Ym1 and decreased the mRNA level of M1 subtype markers CD68, CD86, and iNOS in the tissues around glioma, in vivo (*P < 0.05 and **P < 0.01 vs. Vehicle)." (PMID 33330047, 2020). "This study demonstrated that inhibition of miR-454-3p in glioma cells promoted M2 macrophage polarization, corresponding to elevated expression of II1b, Cd86, and Nos2, and reduced expression of Cd163, Ym1 and Mrc1 in macrophages." (PMID 33363140, 2020). "It has been reported that one potential mechanism of immune paralysis is low expression of MHC-I, MHC-II, CD80, and CD86 in glioma cells, which prevents normal antigen recognition." (PMID 28641579, 2017). "Active glioma Tregs can bind to CD80/CD86 via CTLA-4, suppressing T cell activity." (PMID 40071070, 2025). "In addition, CD86 was an unfavorable prognostic biomarker in lower-grade glioma (LGG) and glioblastoma (GBM) patients." (PMID 38154107, 2023). "Several studies have revealed the role of CD86 among glioma patients." (PMID 38154107, 2023). "Interestingly, in a murine glioma model, diclofenac also resulted in higher frequencies of intra-tumoral CD11c+CD86+ DCs." (PMID 31334125, 2019). "In our study, HOE642 treatment inhibited stimulation of M2 phenotypes of TAMs by reducing protumoral CD206+ TAMs in both resident microglia TAMs and peripheral TAMs (p < 0.05), and increasing the ratio of M1/M2 TAMs (CD16/32+/CD206+ or CD86+/YM1+) in gliomas (p = 0.09 and p = 0.07, respectively)." (PMID 30333031, 2018). "While this may represent a well-balanced equilibrium under healthy conditions, the tumor setting leads to its disruption with upregulation of inhibitory ligands like PD-L1 on glioma cells and CD86 on GAMs, leading to the dysfunctional state seen in the glioma-residing CD8+ Trm cells." (PMID 38127790, 2023). "The study also suggested that CD86 may stimulate glioma malignancy." (PMID 38154107, 2023). "Also, CD86 is an unfavorable prognostic biomarker in lower-grade glioma." (PMID 35359663, 2022). "In another study, a triple-membrane hybrid composed of erythrocytes, U251 glioma cells, and macrophages integrated key membrane markers from each source—CD47 for immune evasion, CD44 for glioma targeting and BBB transport, and CD86 for immune modulation." (PMID 40624508, 2025).
glioma (continued). "We observed that significant upregulation of mRNA expression levels for three TAM markers, MSR1/CD204, CD86, and CD68, suggested that TGFB2 is pivotal in establishing a pro-tumorigenic TME in gliomas mediated through TAMs." (PMID 38539537, 2024). "Alongside these morphological shifts, CMs from glioma cells also enhanced the expression of surface marker CD206, instead of CD86, indicating a shift towards M2-like polarization, evidenced by immunofluorescent staining." (PMID 38576043, 2024). "The GASC score was positively correlated with PD-1, PD-L1, PD-L2, TL1A, TIM3, Galactin-9, CTLA-4, CD80, CD86, CD155, LAG3, and CIITA in all glioma population and the HGG population." (PMID 33996602, 2021). "Given that CD86, LGALS9, and TGFB1 play immunosuppressive roles in glioma, we further investigated the expressing relationship between C1RL and these immunosuppressive genes." (PMID 32993564, 2020). "The levels of the marker for the general activated microglia, CD68, markers for M1 microglia (CD86 and MHC II) and markers for M2 microglia (CD206 and CD163) were all increased in GL261-C glioma tissue than in GL261-eGFP and GL261-vC glioma tissues." (PMID 32550897, 2020). "Consistent with the results from mouse studies, we showed that glioma-CM-pretreated human ECs stimulated human monocytes toward alternative activation, as evidenced by increased CD206+CD86+ populations in CD11b+ cells." (PMID 29422647, 2018). "The enhanced expression of CD86 and reduced expression of CD163 in microglia suggested that HEC1‐derived glioma cells could promote M2 polarization." (PMID 39021287, 2024). "The treatment with CMs from glioma cells resulted in elevated expressions of M2-macrophage markers CD206 and CD163, while showing no significant alterations in the M1-macrophage markers CD80 and CD86." (PMID 38576043, 2024). "Polychromatic immunofluorescence revealed that SIRPB1 co-localizes with TMEM119 (microglia marker), CD86 (M1 macrophage marker), and CD163 (M2 macrophage marker) indicating that SIRPB1 is predominantly found in TAMs, which in glioma tissues exhibit both M1 and M2 characteristics." (PMID 38594692, 2024). "The expression of CD86 and CD8 increased in IDH1mt-glioma tissues in the short-term survival group." (PMID 36159801, 2022). "Similarly, we detected the expression of the M1 biomarker CD86 and the CD8 T-cell biomarker CD8 in glioma tissues using IHC." (PMID 36159801, 2022). "Grade-II glioma showed the same trend between histological types, with no statistical difference detected in CD86 expressions between astrocytoma and oligoastrocytoma." (PMID 33954112, 2021). "CD86, LGALS9, and TGFB1 play immunosuppressive roles in glioma." (PMID 32993564, 2020). "However, it has been reported that glioma cell lines-derived exosomes lack antigen-presentation and the surface co-modulatory machinery CD80 and CD86 able to cross-react with CD28." (PMID 28107450, 2017). "This has been confirmed by in vitro analyses showing induction of MHC class II molecules, CD80, CD86 and IL-12 in co-culture experiments of DCs and PDT-treated mouse tumour cells or DCs and acid-eluted material from PDT-treated C6 rat glioma cells." (PMID 21863026, 2011). "Glioma-infiltrating microglia/macrophages from postoperative tissue samples of glioma patients expressed surface MHC-II but lacked the expression of the co-stimulatory molecules CD86, CD80, and CD40, which are critical for T cell activation." (PMID 40281508, 2025). "CLIC4 expression levels were positively correlated with specific markers of macrophages (CD80, CD86, MRC1), neutrophils (FCGR3A, FCGR3B), eosinophils (SIGLEC8, IL3RA), T cells (CD3D, CD4), CD8+ T cells (CD8A, CD8D), NK cells (NCAM1), and B cells (CD19) in glioma." (PMID 39595145, 2024). "Coculture of mature and immature cells with glioma cells does not change their phagocytic capacity but could diminish their surface expression of MHC and CD86." (PMID 37296865, 2023).